LIPC (lipase C, hepatic type)
Diseases named in the same sentence as LIPC in open-access papers (continued):
Sharing a sentence is not in itself a finding about the gene and the disease.
age-related macular degeneration (10 papers, 2010 to 2025). Age-related loss of vision in the central portion of the retina (macula), secondary to retinal degeneration. "Phosphatidylethanolamine-increasing LIPC variants seemed to lower age-related macular degeneration risk independently of HDL-cholesterol." (PMID 40157129, 2025). "We show that LIPC variants increase Phosphatidylethanolamines and lower age-related macular degeneration risk independently of HDL-cholesterol." (PMID 40157129, 2025). "The purpose of this study was to evaluate the association of the hepatic lipase (LIPC) rs493258 polymorphism and susceptibility to age-related macular degeneration (AMD)." (PMID 27763569, 2016). "Distribution of demographic and behavioral risk factors for advanced age-related macular degeneration and controls according to hepatic lipase-C (LIPC) genotypes." (PMID 21139980, 2010). "In addition, two LIPC SNPs were found to be associated with advanced age-related macular degeneration (AMD), whose progression was characterized by a hallmark of age-related oxidative changes." (PMID 31077211, 2019). "Multivariate analyses of associations between advanced age-related macular degeneration (AMD), hepatic lipase-C (LIPC) genotypes, and demographic, genetic, and behavioral risk factors." (PMID 21139980, 2010). "A novel locus in the hepatic lipase (LIPC) gene was found to be significantly related to advanced age-related macular degeneration (AMD) in our genome-wide association study." (PMID 21139980, 2010). "Assessment of effect of interactions between hepatic lipase-C (LIPC) genotype and lifestyle factors on risk of age-related macular degeneration (AMD)." (PMID 21139980, 2010). "Assessment of effect of interactions between hepatic lipase (LIPC) genotype (rs10468017) and other genes on risk of age-related macular degeneration." (PMID 21139980, 2010). "Lipid metabolism genes such as APOE, ABCA1, LIPC, and CETP play fundamental roles in the pathogenesis of age-related macular degeneration (AMD) by influencing lipid transport, cholesterol efflux, and lipoprotein remodeling within the retinal pigment epithelium (RPE) and Bruch’s membrane." (PMID 40331961, 2025).
Hepatic steatosis (9 papers, 2013 to 2025). Steatosis is a term used to denote lipid accumulation within hepatocytes. "Two patients with LIPC variants had elevated ALT levels consistent with fatty liver disease." (PMID 39518997, 2024). "Upregulation of ADRP levels, PNPLA3/ADI polymorphisms, liver lipase (LIPC/HTGL) and lysophospholipase-like protein 1 (LYPLAL1) gene mutations, and DGAT2 enzymes involved in TG synthesis are also associated with the risk of liver steatosis." (PMID 33147895, 2020).
Hypercholesterolemia (9 papers, 2013 to 2023). An increased concentration of cholesterol in the blood. "LIPC C-514T and PPAR-alpha L162V carriers could benefit from a plant sterol supplement to ameliorate hypercholesterolemia." (PMID 31640222, 2019).
diabetes (8 papers, 2011 to 2023). "This polymorphism was independently associated with an increased risk of diabetes (OR: 1.828; IC 95%: 1.12–2.99; p = 0.016), even after adjusting by confounding variables, whereas the LIPC polymorphism was not." (PMID 22073289, 2011).
coronary atherosclerosis (6 papers, 2013 to 2022). Atherosclerosis of the coronary vasculature. "Interestingly, the strength of association of LIPC variants with coronary atherosclerosis is considerably increased when conditioned on clinical lipids (both standard adjustment and mtCOJO analyses) further supporting a direct mechanistic link." (PMID 35668104, 2022). "Interestingly, in the large secondary prevention REGRESS study, it was demonstrated that patients having a combination of defective alleles for CETP and LIPC, displayed high HDL levels but also the highest progression of coronary atherosclerosis." (PMID 23874450, 2013).
Hypertension (6 papers, 2016 to 2023). The presence of chronic increased pressure in the systemic arterial system. "A study using the meta-analysis approach has shown that rs2070895 in LIPC was associated with an increased risk of hypertension." (PMID 37273686, 2023). "LIPC variant rs2070895 has been found to be associated with carotid atherosclerosis and hypertension." (PMID 37273686, 2023). "In summary, the present study showed that the frequencies of the AA+GA genotypes of the LIPC rs2070895 polymorphism are related to an increased risk of hypertension." (PMID 30322388, 2018). "The present study was conducted to analyze the correlation of LIPC rs2070895 and rs1800588 polymorphisms with the susceptibility to hypertension in all genetic inheritance models." (PMID 30322388, 2018). "The LIPC rs2070895 polymorphism was found to be related to an increased risk of hypertension." (PMID 30322388, 2018). "Notably, the frequencies of the AA+GA genotypes of LIPC rs2070895 polymorphism were related to an increased risk of hypertension (AA+GA vs. GG, OR = 1.1954, 95% CI: 1.0001–1.4288, P = 0.05)." (PMID 30322388, 2018). "Notably, our results showed that LIPC rs2070895 polymorphism were significantly related to an increased hypertension risk under the dominant model (AA+GA vs. GG, OR = 1.1954, 95% CI: 1.0001–1.4288)." (PMID 30322388, 2018). "Because the OR values in all models were larger than 1, gene A under the dominant model in LIPC rs2070895 polymorphism may be a dominant risk factor for the susceptibility to hypertension." (PMID 30322388, 2018). "Interestingly, our study revealed that the LIPC rs2070895 polymorphism was strongly related to an increased hypertension risk under the dominant model (AA+GA vs. GG)." (PMID 30322388, 2018). "In this meta-analysis, we pooled related studies of the frequency distribution of LIPC -250G/A (rs2070895) and -514C/T (rs1800588) polymorphisms in hypertension patients and normal individuals to assess the relationship of LIPC gene polymorphisms and hypertension risk." (PMID 30322388, 2018). "Therefore, the LIPC rs2070895 polymorphism may be a risk factor for the susceptibility to hypertension." (PMID 30322388, 2018). "Thus, LIPC polymorphisms may be closely associated with increased risk of hypertension by regulating HDL, LDL, and other lipid metabolism levels." (PMID 30322388, 2018). "This meta-analysis aimed to explore the association between hepatic lipase gene (LIPC) gene -250G/A (rs2070895) and -514C/T (rs1800588) polymorphisms and the susceptibility to hypertension." (PMID 30322388, 2018). "An increasing number of studies has focused on LIPC gene and hypertension." (PMID 30322388, 2018). "The LIPC rs1800588 polymorphism did not appear to be associated with an increased risk of hypertension." (PMID 30322388, 2018). "Many reports showed that CETP, LIPC and LIPG were associated with HDL and LDL and that MTHRR had known main effects for LDL and blood pressure, NR1I3 for lipid metabolism, PLTP for LDL, FOXO1 for LDL and hypertension, SMAD9 for hypertension, and CSMD1 for SBP." (PMID 27104857, 2016).
myocardial infarction (5 papers, 2013 to 2023). Gross necrosis of the myocardium, as a result of interruption of the blood supply to the area, as in coronary thrombosis. "Of note, one recent and among the largest meta-analyses dealing with SNPs affecting HDL-cholesterol found an association of LIPC rs1800588 with myocardial infarction." (PMID 23874450, 2013). "In addition, it has been elucidated that LIPC exhibits a gene-level association with myocardial infarction." (PMID 37273686, 2023).
dyslipidaemia (4 papers, 2010 to 2022). "We found that as the proportion of protein decreases, the prevalence of CCD increases in dyslipidaemia patients with the GG/GA type of the LIPC gene." (PMID 35884923, 2022).
hepatocellular carcinoma (4 papers, 2022 to 2025). A malignant tumor that arises from hepatocytes. "Down-regulation of TUSC3 promotes EMT progression by activating AKT signaling via targeting LIPC in HCC, which is probably the possible mechanism driving TUSC3-deficient hepatocellular carcinoma cells toward a malignant phenotype." (PMID 36274132, 2022). "Our preliminary studies found that an FXR agonist could inhibit the transcription of hepatic lipase (HL, encoded by LIPC) in a dose‐ and time‐dependent manner in human hepatoma HepG2 cells and inhibit HL activity." (PMID 39601316, 2025).
Stroke (4 papers, 2011 to 2023). Sudden impairment of blood flow to a part of the brain due to occlusion or rupture of an artery to the brain. "The correlation between LIPC polymorphisms and stroke risk was measured by odds ratio (OR) and 95% confidence interval (CI)." (PMID 37273686, 2023). "Our research has shown that rs690 and rs6074 in LIPC were associated with an increased risk of stroke in male patients." (PMID 37273686, 2023). "The relationship between LIPC polymorphisms and 42 clinical parameters of stroke patients was also investigated in the study." (PMID 37273686, 2023). "Multifactor dimensionality reduction analysis was performed to further explore the impact of LIPC SNP-SNP interaction on stroke risk." (PMID 37273686, 2023). "The purpose of this study was to explore the association between LIPC single nucleotide polymorphisms (SNPs) and the risk of stroke in the Chinese population." (PMID 37273686, 2023). "This study indicated that rs690 and rs6074 in LIPC were significantly associated with increased risk of stroke in the Chinese population, possibly by regulating the levels of PDW, HCT, and LDL-C." (PMID 37273686, 2023). "First, this study is the first to explore the relationship between LIPC polymorphisms and stroke susceptibility in the Chinese population." (PMID 37273686, 2023). "This study was the first to reveal that LIPC polymorphisms were associated with the risk of stroke in the Chinese population." (PMID 37273686, 2023). "The main LIPC-related protein–protein interactions were connected with lipid metabolism, which is expected to provide a new direction for investigating the effect of LIPC on stroke risk." (PMID 37273686, 2023). "In this study, a total of 710 stroke patients and 701 controls were recruited to explore the correlation between LIPC polymorphisms and the risk of stroke in the Chinese population." (PMID 37273686, 2023). "This study further clarified the correlation between LIPC polymorphisms and the risk of stroke in the Chinese population after stratification analysis by age, gender, and smoking and drinking status." (PMID 37273686, 2023). "Relationships of LIPC gene polymorphisms with the risk of stroke stratified by smoking and drinking." (PMID 37273686, 2023). "This is the first study to analyze the relationship between LIPC polymorphisms and the risk of stroke in the Chinese population." (PMID 37273686, 2023). "Therefore, this study was undertaken to detect the association between LIPC polymorphisms and the risk of stroke from 710 patients with stroke and 701 healthy controls in the Chinese population." (PMID 37273686, 2023). "However, there are very few studies on the correlation between LIPC polymorphisms and the risk of stroke." (PMID 37273686, 2023). "However, no statistical significance was found between the genotypes of the three SNPs (rs6083, rs3829461, and rs6074) in LIPC and the risk of stroke (p > 0.05)." (PMID 37273686, 2023). "Relationships of LIPC polymorphisms with stroke risk stratified by gender and age." (PMID 37273686, 2023). "Relationships between LIPC polymorphisms and stroke risk under multiple genetic models." (PMID 37273686, 2023). "Therefore, we speculated that rs690 in LIPC modified the risk of stroke by modulating PDW and/or HCT levels." (PMID 37273686, 2023). "The analysis, which included 14,746 African Americans, found a novel SNP associated with total stroke in the 15q21.3 locus which is located near the Aquaporin 9 gene (AQP9), the aldehyde dehydrogenase 1 family, member A2 (ALDH1A2) and hepatic lipase (LIPC) genes." (PMID 34828431, 2021). "The authors found 5 polymorphisms (one in CETP and 1 in LIPC) that had significant interactions with statins on stroke outcome, the highest significance level was found in the CETP SNPs (rs5883), which was associated with stroke risk in simvastatin users." (PMID 22135769, 2011).
Stroke (continued). "Our bioinformatics analysis results indicated that the expression levels of LIPC and its related genes (APOB, CETP, PNPLA2, and LMF1) showed significant differences between stroke and control groups." (PMID 37273686, 2023). "Based on the Gene Expression Omnibus (GEO) database analysis, significant differences in the expression levels of LIPC, APOB, CETP, PNPLA2, and LMF1 between the control and stroke groups were observed." (PMID 37273686, 2023). "Furthermore, bioinformatics analysis results demonstrated that the expression levels of LIPC and its related genes (APOB, CETP, PNPLA2, and LMF1) were significantly different between the control and stroke groups (p < 0.05), and LIPC-related proteins were mainly related to lipid metabolism." (PMID 37273686, 2023). "Third, we only predicted the signal pathway that LIPC might participate in through the databases, and the impact of SNPs on the LIPC gene mRNA level and the function of LIPC in stroke have not been explored in this study." (PMID 37273686, 2023).
Alzheimer disease (3 papers, 2012 to 2019). A progressive, neurodegenerative disease characterized by loss of function and death of nerve cells in several areas of the brain leading to loss of cognitive function such as memory and language. "Finally, in the broader context of traits potentially related to cognition, we find an enrichment of HHMCs in genes associated to “Alzheimer’s disease (cognitive decline)” and “Cognitive decline (age-related)”, with seven associated genes (COX7B2, BCAS3, DMXL1, LIPC, PLEKHG1, TTLL2 and VIT)." (PMID 31186485, 2019). "In addition, LIPC has been reported to exhibit gene-gene interaction with other genes associated with lipid traits, and HMGCR has been reported to interact with ABCA1 in Alzheimer's disease risk." (PMID 22654671, 2012).
hepatic lipase deficiency (3 papers, 2016 to 2025). "Hepatic lipase deficiency: Genetic loss-of-function variants in the LIPC gene causes hepatic lipase deficiency in an autosomal recessive manner." (PMID 40004987, 2025). "LIPC rs28933094 predisposes to hepatic lipase deficiency, the cardiovascular effects of which are unclear but may be dependent on the underlying lipid phenotype." (PMID 27227539, 2016).
non-small cell lung carcinoma (2 papers, 2022 to 2023). A group of at least three distinct histological types of lung cancer, including non-small cell squamous cell carcinoma, adenocarcinoma, and large cell carcinoma. "Studies propose LIPC's involvement in malignancies; for instance, low LIPC expression correlates with improved prognosis in platinum-based chemotherapy for non-small cell lung cancer." (PMID 38192945, 2023). "In the context of non-small cell lung carcinoma (NSCLC), LIPC expression levels may have both a predictive value and an independent prognostic potential." (PMID 36274132, 2022).
pancreatic cancer (2 papers, 2021 to 2023). "LIPC, a gene promoting pancreatic cancer metastasis, is implicated in tumor cell migration and invasion." (PMID 37426677, 2023). "In metastatic pancreatic cancer cells, the number of chromatin loops increases LIPC expression is modulated by Enhancer 3 and Enhancer 4, while tissue‐specific chromatin loops form progressively during pancreatic cancer distant metastasis." (PMID 37426677, 2023). "LIPC expression is modulated by Enhancer 3 and Enhancer 4, while tissue‐specific chromatin loops form progressively during pancreatic cancer distant metastasis, enhancing LIPC expression." (PMID 37426677, 2023). "We found that LIPC expression was significantly higher in liver metastasis than primary pancreatic cancer." (PMID 34348759, 2021). "The primary tumor weights, liver weights, and the pancreatic cancer cells with liver metastasis were also lower in LIPC silenced group." (PMID 34348759, 2021). "Together, our results demonstrated that loop reprogramming cause LIPC upregulation during pancreatic cancer metastasis, and confirmed an important role of LIPC in pancreatic cancer metastasis clinically and functionally." (PMID 34348759, 2021). "Wound-healing assays and transwell assays showed that LIPC overexpression promoted but LIPC knockdown inhibited pancreatic cancer cells migration and invasion." (PMID 34348759, 2021). "By combining our Hi-C data, we identified the key gene, LIPC, looped to Capan-1 specific enhancers and significant upregulated in metastasis lesions of pancreatic cancer." (PMID 34348759, 2021). "To test the effect of LIPC on pancreatic cancer metastasis, we used plasmids or lentivirus (Lv) to increase LIPC expression and siRNAs or shRNAs to reduce LIPC expression." (PMID 34348759, 2021). "GEO datasets and our IHC analysis demonstrated that LIPC expression was significantly higher in liver metastasis compared with primary pancreatic cancer and normal pancreatic tissues." (PMID 34348759, 2021). "Similarly, LIPC expressed higher in primary pancreatic cancer than tumor-adjacent normal pancreatic tissues." (PMID 34348759, 2021).
arteriosclerosis (1 paper, 2023). A vascular disorder characterized by thickening and hardening of the walls of the arteries. "However, a univariate analysis did find that 44% of patients with subclinical arteriosclerosis show at least one A allele in the LIPC gene, as compared to only 34% of patients who had no burden." (PMID 36759767, 2023).
breast carcinoma (1 paper, 2018). "We found that both LPL and LIPC were underexpressed in invasive ductal carcinomas (IDCs) and were not differentially expressed among distinct molecular breast cancer subtypes." (PMID 29350614, 2018).
carotid atherosclerosis (1 paper, 2023). A thickening and loss of elasticity of the walls of carotid arteries that occur with formation of atherosclerotic plaques. "Some research studies have also shown an association between some variants of the hepatic lipase gene (LIPC) promoter and the presence of PAD and carotid atherosclerosis." (PMID 36759767, 2023).
Cirrhosis (1 paper, 2025). A chronic disorder of the liver in which liver tissue becomes scarred and is partially replaced by regenerative nodules and fibrotic tissue resulting in loss of liver function. "Among all, the top 5 hub genes identified for NAFLD vs. control were CXCL9, NOS2, SERPINE1, FABP4, and LPL, whereas AKR1D1, UGT2B17, CYP26B1, LIPC, and DGAT2 were identified as the top 5 hub genes for the NAFLD vs. cirrhosis group." (PMID 40365443, 2025). "Additionally, the top 5 biological functional hub genes in NAFLD vs. control (CXCL9, NOS2, SERPINE1, FABP4, and LPL) and NAFLD vs. cirrhosis (AKR1D1, UGT2B17, CYP26B1, LIPC, and DGAT2) groups were identified through PPI analysis among lipid, immune, and metabolism dysregulated genes." (PMID 40365443, 2025).
demyelinating disease (1 paper, 2022). A broad group of disorders that affect the myelin sheaths that cover the neurons. "However, changes in LPGAT1 and LIPC, which act only on LPC 18:1 but not LPC 18:0, alone can account for the observed deficiency or absence of LPC 18:1, thus suggesting the importance of lipid metabolism in demyelinating disease pathology." (PMID 35027445, 2022).
gastric cancer (1 paper, 2023). A primary or metastatic malignant neoplasm involving the stomach. "The connection between LIPC and LIPF, known for its involvement in lipid metabolic processes and downregulation in gastric cancer, added another layer of complexity to the potential role of LIPC in HNSCC." (PMID 38192945, 2023).